CNFN (cornifelin)
Description:
Part of the insoluble cornified cell envelope (CE) of stratified squamous epithelia.
Synonyms: PLAC8L2
Tractability: Antibody: its Gene Ontology location is reachable by antibodies, with high confidence.
Gene: Protein-coding gene on chromosome 19 (42,387,019 to 42,390,297, reverse strand). Ensembl gene ENSG00000105427.
Subcellular location: Cytoplasm
Subcellular location (Human Protein Atlas): Microtubules; Cytokinetic bridge
Gene Ontology:
Molecular function: protein binding
Cellular component: cornified envelope; cytoplasm
Genetic constraint (gnomAD): Loss-of-function variants: 10 observed, 11.59 expected, observed/expected ratio (o/e) 0.86, 90% interval 0.53 to 1.46. The upper end of that interval is the gene's LOEUF score, 1.46, which puts it in group 6 of 6, group 1 being the genes least tolerant of losing a copy. Missense variants: 165 observed, 146 expected, observed/expected ratio (o/e) 1.13, 90% interval 1 to 1.29. Synonymous variants: 66 observed, 55.73 expected, observed/expected ratio (o/e) 1.18, 90% interval 0.97 to 1.45.
Homologues: Orthologues: chimpanzee CNFN (100% identical), macaque CNFN (100% identical), dog CNFN (97% identical), mouse Cnfn (96% identical), pig CNFN (96% identical), rabbit CNFN (95% identical), guinea pig CNFN (94% identical), rat Cnfn (76% identical), tropical clawed frog cnfn (56% identical), tropical clawed frog cnfn.4 (51% identical), tropical clawed frog cnfn.2 (50% identical), tropical clawed frog cnfn.3 (47% identical), and 1 more. Paralogues in human: PLAC8L1 (39% identical), PLAC8 (37% identical).
Diseases named in the same sentence as CNFN in open-access papers:
CNFN is named in the same sentence as 13 diseases in open-access papers, as found by Europe PMC text mining. Sharing a sentence is not in itself a finding about the gene and the disease. The quoted sentences say what the papers report.
ichthyosis (2 papers, 2016 to 2024). Disorders of cornification that are characterized by visible scaling and/or hyperkeratosis of most or all of the skin. "In conclusion, we detail the cases of 2 brothers with autosomal recessive congenital ichthyosis associated with and likely resulting from a novel pathogenic variant in the CNFN gene." (PMID 39282523, 2024).
alopecia (1 paper, 2017). Hair loss usually from the scalp. "However, we did not observe any alteration in Zdhhc13 level suggesting that the development of cyclic alopecia in K14-sPLA2-IIA homozygous mice is independent of cornifelin deficiency mediated cyclic alopecia as shown in Zdhhc13 mutant mice." (PMID 28912581, 2017).
coronary artery disease (1 paper, 2014). "Other genes in this region include CIC, which is a transcriptional suppressor involved in early organ development, CNFN (involved in hematopoiesis), CXCL17 (involved in angiogenesis), and PAFAH1B3 (related to coronary artery disease and organ development)." (PMID 24555826, 2014).
lymph node metastasis (1 paper, 2023). "Notably, after comparing the expression levels of CNFN between patients with lymph node metastasis (LNM +) and those without lymph node metastasis (LNM-), it was indicated that LNM- patients had significantly higher CNFN expression levels." (PMID 37907576, 2023).
tumor (3 papers, 2023 to 2025). "In contrast, Tum_3 tumor cells primarily expressed genes linked to epithelial differentiation and keratinization, such as CNFN, EPS8L1, and HEPHL1." (PMID 40470730, 2025). "Additionally, we investigated the potential mechanisms through which CNFN could influence tumor-associated LNM." (PMID 37907576, 2023). "The tumor subtypes reflected by the patient-derived ex vivo cultures were validated by qPCR analysis of keratinization (CNFN, CRNN), basal (KRT5, KRT6), and luminal markers (KRT7, GATA3)." (PMID 41387887, 2025). "The present study found a decrease in CNFN expression in tumor tissues of HNSCC patients with LNM, providing the first evidence of CNFN as a tumor suppressor gene, inhibiting the proliferation, migration, and invasion abilities of HNSCC cell lines." (PMID 37907576, 2023). "Additionally, the functional role of one of the gene signatures, CNFN, in HNSCC, along with its potential mechanisms underlying tumor-associated LNM, was elucidated." (PMID 37907576, 2023). "The eight genes (CAMK2N1, WNT7A, F2RL1, AREG, DEFB1, CNFN, TGFBI, and CAV1) included in the signature have been extensively studied and are known to be involved in tumor progression and EMT process." (PMID 37907576, 2023).
skin disorder (1 paper, 2016). Any deviation from the normal structure or function of the skin or subcutaneous tissue that is manifested by a characteristic set of symptoms and signs. "It is interesting that many of the changes in gene expression found in HaCaT-IKKα skin equivalents are relative to genes involved in the development of different skin disorders (CNFN, CDSN, TGM1, ALOX12B, etc)." (PMID 27732959, 2016).
CNFN also shares sentences with these, for which no sentence is quoted: psoriasis (2 papers); autosomal recessive congenital ichthyosis (1); cancer (1); congenital ichthyosis (1); dermatitis (1); eczema (1); squamous carcinomas (1).